NOX4 (NADPH oxidase 4)
Diseases named in the same sentence as NOX4 in open-access papers (continued):
Sharing a sentence is not in itself a finding about the gene and the disease.
cancer (continued). "Moreover, reactive oxygen species (ROS) production was also increased by TGF-β downregulation, which triggered Akt inactivation and NOX4 increase-derived ROS in a cancer cell-type-specific manner." (PMID 30523245, 2018). "In summary, our data suggest that NOX4 inhibition may have broad applicability for stromal targeting across cancer types." (PMID 28922779, 2018). "Similarly, simultaneous depletion of NOX1 and NOX4 also reduced the ROS level in cancer cells treated with PJ-34." (PMID 29684820, 2018). "Taken together, these observations strongly indicated that NOX4 may be a cancer promoter for CRC and may play an important role in CRC progression." (PMID 28422720, 2017). "Thus, it is likely that NOX1 is upregulated to promote cancer progression during stress situations, while NOX4 is a factor that produces ROS which contributes to cellular injury and senescence." (PMID 28423654, 2017). "Nox4 was found to be expressed in several tested cancers and cancer cells lines." (PMID 28620580, 2017). "NOX4 is also reported to contribute to progression and metastasis in various cancers." (PMID 28099519, 2017). "Suppression of NOX4 by siRNA in PDAC cells decreased NADH oxidation and cellular NAD+ levels, glycolysis and cellular ATP production, and ultimately caused the interruption of cancer growth." (PMID 28232723, 2017). "Therefore, it is encouraging to block Nox4 pharmacologically as a means to counteract the metastatic potential of cancer cells." (PMID 28620580, 2017). "In addition, NOX4 overexpression was detected in the cancer tissues of patients with low- or high-grade and non-invasive or invasive urothelial cancers, including carcinoma in situ, as compared to normal urothelium." (PMID 29065504, 2017). "As far as we are aware, this is the first report to study the NOX4 knockout in human cancer cells." (PMID 28099519, 2017). "We propose that inhibition of Nox4 (which is known to be strongly expressed in many tumors) could be studied as a new target for cancer treatment, in particular for inhibition of metastasis." (PMID 28620580, 2017). "Our findings suggest that NOX4 is a potential therapeutic target for cancer therapy." (PMID 28232723, 2017). "Many reports have been published about the role of NOX4 in human cancers." (PMID 28099519, 2017). "In addition, there is reason to suspect that Nox4 activation is a mediator of the feed-forward mechanism whereby release of TGF-beta from bone matrix by osteolysis promotes expression of PTHrP in cancer cells, and thereby induces further osteolysis." (PMID 27571113, 2016). "NOX4 has been confirmed to promote cell aggressiveness of various types of cancer." (PMID 24946933, 2014). "Nox4 co-localizes with α-actin in smooth muscle cells and is found in actin-rich invadopodia of cancer cells, suggesting that Nox might be involved in the S-glutathionylation and redox regulation of actin." (PMID 23825596, 2013). "Moreover, silencing of NOX4 by siRNA significantly reduced cancer cell growth in vivo as assessed in an orthotopic mouse model." (PMID 22032647, 2011). "Moreover, NOX4 silencing reduced ROS generation and suppressed cancer cell growth via p16-dependent cell cycle arrest at the G1 phase, both in vitro and in vivo." (PMID 22032647, 2011). "In the present study, we show that NOX4 maintained intracellular generation of ROS in both high and low grade and superficial and invasive urothelial carcinoma cells and contributes to cancer cell survival, using in vitro and in vivo experiments and clinicopathological analyses." (PMID 22032647, 2011). "Therefore, we discuss the discuss the contribute of NOX1, NOX2, and NOX4 enzymes in the modulation of cellular metabolism and highlight their potential role for new therapeutic approaches that target the rewired metabolism of cancer cells." (PMID 36768405, 2023). "In conclusion, NOX4 might have various functions in various cancers." (PMID 37626693, 2023).
cancer (continued). "NOX4 may also promote the resistance of cancer cells to chemotherapeutic agents and radiotherapy." (PMID 36874093, 2023). "In PTC, NOX4 expression is significantly higher in the presence of the BRAFV600E mutation, the most frequent genomic alteration found in PTC, present in around 40–60% of cases and associated with increased cancer-related mortality and thyroid cell dedifferentiation, as well." (PMID 37891977, 2023). "Inhibition of Nox4, therefore, might prevent the survival of an existing cancer cell." (PMID 30737851, 2019). "Here, we report a molecular axis, comprising the molecular adaptor hydrogen peroxide-inducible clone-5 (HIC-5), NADPH oxidase 4 (NOX4), and mitochondria-associated reactive oxygen species (mtROS), that regulates MMP9 expression and may be a target to suppress cancer metastasis." (PMID 30281903, 2018). "The downstream target of NOX4, which mediates drug resistance in cancer cells is unknown." (PMID 29051480, 2017). "Therefore, based on these results, regulation of NOX4-driven mitochondrial ROS production could be a potential target for development of the cancer therapy and management." (PMID 27405931, 2016). "For example, EAS-specific unambiguous probes (n = 484) from the HM450K array were overlapped with promoters and gene bodies of 140 cancer driver genes, such as CTNNB1, DSP, FRK, HLA-A, NOX4, and TRIO." (PMID 40445831, 2025). "NOX4 showed the highest frequency of methylation, while the expression of SOCS1 positively correlated with the promoter methylation across 20 types of cancer in TCGA." (PMID 40463869, 2025). "In the TCGA cohort, it was depicted by a correlation between several MMPs mRNA expression in cancer tissue with NOX2 and NOX4 transcript level." (PMID 38397798, 2024). "The results show that NOX4 was found to be higher (score ≥ 2) in C-PTC (92.9%) compared to F-PTC (52.9%) and ATC (33.3%) concerning malignant tumors." (PMID 37504283, 2023). "Inhibition of ROS generation via the targeting of mitochondria and NOX4 blocks EMT progression and metastasis in various cancers." (PMID 35799889, 2022). "Setanaxib, a selective NOX4 inhibitor, is a critical ROS inhibitor undergoing clinical trials for cancer therapies, while H2O2 was a strong ROS promoter in cancer cells." (PMID 36211828, 2022). "NOX4 is an important source of ROS induced by TGF-β and under hypoxia, two important mediators in cancer metastasis." (PMID 36359304, 2022). "Cancer cells have elevated expression levels of NOXs (NOX1, NOX2, NOX4, NOX5), leading to high levels of ROS." (PMID 36359304, 2022). "NOX1 is well recognized in its role in promoting angiogenesis, making the inhibition of both the NOX1 and NOX4 enzymes by GKT137831, an attractive therapeutic option for cancers." (PMID 35836253, 2022). "To date, the interconnection between H2O2 signaling and EMT in cancer is well established, and the role of H2O2 producers NADPH oxidase 4 (NOX4), dual oxidase 1 (DUOX1) and DUOX2 in cell motility and metastasis in cancer biology has been reviewed." (PMID 35873564, 2022). "Inhibiting NOX4 expression effectively suppressed MMP-3 expression, gemcitabine resistance, and cancer invasion." (PMID 36211828, 2022). "ROS stimulates antioxidation signal pathways to enhance the survival and proliferation of cancer.In PDA, ROS level is mainly regulated by NADPH oxidase 4 (NOX4)." (PMID 36211828, 2022). "Mitochondria and NOXs family, including NOX1, NOX2, NOX3, NOX4, NOX5, DUOX1, and DUOX2, are two important sources of ROS production in cancer cells." (PMID 35418176, 2022). "NOX4, a member of NADPH oxidase (NOX), has been found to be activated by hypoxia and promote cancer progression in several cancers." (PMID 33499904, 2021). "This allowed the selection of the key EMT-correlated genes that uncover functional implications in cancer; this is the case of direct correlation of NOX4 with DACT3 and SFRP1 and inverse correlation of NOX4 and BMP5." (PMID 34073426, 2021).
cancer (continued). "NADPH oxidase 4 (NOX4) is a NOX family isoform that constitutively produces ROS and is involved in multiple biological functions during cancer progression." (PMID 34740322, 2021). "On the other hand, the inhibition of JNK pathway repressed the c-Jun phosphorylation and NOX4 expression, followed by the inhibition of ROS production, MMP-1 and MMP-9 expression, and invasion ability in OA-treated cancer cells." (PMID 32641980, 2020). "To identify circRNAs with a putative function in ccRCC initiation/progression, we selected circRNAs from host genes with putative roles in angiogenesis and hypoxia in ccRCC and other cancers including EGLN3, NOX4, and RHOBTB3." (PMID 31575051, 2019). "Mitochondria and NADPH oxidases of the Nox family including NOX1, NOX2, NOX3, NOX4, NOX5, DUOX1 and DUOX2, are two important sources of ROS production in cancer cells." (PMID 30755243, 2019). "Upon detachment of cancer cells from the BM/ECM, NOX4 is upregulated by TGF-β1 and angiotensin II and induction of EMT via the TGF-β1-NOX4 axis occurs via p38 MAPK signalling." (PMID 31198853, 2019). "The SRC proto-oncogene has been demonstrated to activate NADPH oxidases NOX1-, NOX3-, NOX4-, and NOX5-induced O2•− production in cancer models and to increase mutant SOD1 aggregate formation in ALS." (PMID 29478325, 2019). "The data demonstrate stable and low mRNA expression of NOX1, NOX3, NOX4, and NOX5, whereas the expression of NOX2 is markedly higher and variable in different forms of cancer." (PMID 29478325, 2019). "Generation of a monoclonal antibody to the extracellular domain of NOX4 with sufficient sensitivity and specificity to monitor changes in enzyme expression by Western blot and TMA for levels of cancer expression has proven difficult." (PMID 28578276, 2017). "Hence, the inhibition of Nox4‐depedent redox signalling using HDAC inhibitors may be an interesting approach to investigate several pathological conditions given the success of HDAC inhibitors in the clinic for cancer ablation." (PMID 27297729, 2016). "In these tumors, Nox4 expression correlates with DDR activation, and NOX4 and DDR activation both increase during cancer progression." (PMID 24583638, 2014). "This suggests that SH3YL1 and NOX4 may act cooperatively in MIBC, potentially contributing to the invasiveness of cancer cells through enhanced oxidative stress modulation." (PMID 40362200, 2025). "Data from the cancer genome atlas (TCGA) have shown that cancers of epithelial origin, including skin, lung, prostate, liver, stomach, brain, head and neck, and breast, overexpress one or more NOX enzymes, particularly NOX4 and DUOX1/2." (PMID 39201571, 2024). "Nevertheless, the extent of NOX4’s involvement in different cancer types and its clinical implications have not been systematically explored." (PMID 38663913, 2024). "Our results suggested that NOX4 expression was related to OS and DFS in cancer patients, but this association was not statistically significant." (PMID 35265227, 2022). "Nevertheless, although the results suggested an association between NOX4 expression and DFS in cancer patients, it was not statistically significant." (PMID 35265227, 2022). "Some cancer cells overexpress NOX members, and among them, NOX4 is often." (PMID 35265227, 2022). "NOX4 inhibition could effectively overcome the resistance of CAF-mediated immunotherapy and improve the prognosis of many cancers." (PMID 34007851, 2021).
cancer (continued). "In conclusion, these suggest that NOX4/ROS induction by TGF-β1 can be one of the main mechanisms mediating the metabolic reprogramming during EMT of glioblastoma cells and provide promising strategies for cancer therapy." (PMID 34257808, 2021). "Many types of cultured cancer cell lines and human tumors at early and late stages of tumorigenesis express higher levels of NOX1, NOX2, NOX4, and NOX5 or their regulatory components compared with normal controls, suggesting a pivotal role either in cancer development or in progression." (PMID 34204425, 2021). "However, in some cancer cell types, ADP-ribosylation emerged as an repressor of NOX1 and NOX4 since cell treatment with PJ34 resulted in upregulation of NOX1 and NOX4 mRNAs." (PMID 32900001, 2020). "It is therefore an important aim of cancer research to develop specific inhibitors of Nox4, which has not been achieved up to now, despite testing of a large number of candidate compounds." (PMID 30084091, 2018). "Interestingly, among six cancer cell lines, only EJ-1 and MDA-MB-231 cells exhibited upregulation of NOX4 and MMP9 expression after shRNA-mediated HIC-5 knockdown." (PMID 30281903, 2018). "Nox4 was discovered as an NADPH oxidase highly expressed in kidney, but it is expressed at a low level in a large variety of human tissues, including cancers, cancer cell lines, and embryonic tissues." (PMID 30084091, 2018). "Furthermore, in order to explore the function of Nox4 in cancer ell metabolism of OTSCC, we examined its expression in OTSCC cell lines and we evaluated the effect of Nox4 knockdown on cell proliferation in vitro." (PMID 30513726, 2018). "Furthermore, the increased expression of NOX4 and p22phox in PDAC analysed from multiple cancer microarray data sets available from Oncomine also supports our findings." (PMID 28232723, 2017). "Our findings reveal the novel function of NOX4 in reprogramming aerobic glycolysis initiated by activated Kras and inactivated p16 in PDAC, indicating its potential as a therapeutic target for PDAC and other cancers." (PMID 28232723, 2017). "While most of these studies used the small interfering RNA mediated knockdown system, genomic inactivation of NOX4 has not been reported in cancer cells." (PMID 28099519, 2017). "We demonstrated in this study that enhanced NOX1 and NOX4 expression and ROS production triggered by LTB4/BLT1 signal axis increases the pSmad3L, contributing to the resistance to the TGF-β1 growth-inhibitory effects in cancer cells." (PMID 26497676, 2015). "However, there has been no systematic analysis of the relationship between NOX4 expression and prognosis in cancer patients." (PMID 35265227, 2022). "Interestingly, NADPH oxidase NOX4-synthesized ROS inactivate phosphotyrosine phosphatase PP1α, thereby activating PI3K-AKT signaling and further strengthening CML cell drug resistance and cancer cell survival." (PMID 29478325, 2019). "Pharmacological inhibition of NOX4 (GKT137831) and RNAi-mediated knockdown (shRNA and siRNA) (respectively, available online) abrogated TGF-β-dependent ROS production, myofibroblast transdifferentiation, and cancer cell migration toward conditioned media from treated fibroblasts." (PMID 28922779, 2018). "However, owing to the nature of dual NOX1/NOX4 inhibition of GKT137831, NOX1 siRNA was also used to check the possibility of NOX1 involvement in TGF-β1 downregulation-induced ROS generation/ER stress and subsequent cancer cell death." (PMID 30523245, 2018). "However, mechanisms by which NOX4 regulates cancer cell proliferation, survival and migration are not fully understood." (PMID 28099519, 2017). "In addition, NOX4 stimulates angiogenesis through the upregulation of vascular endothelial growth factor (VEGF)-A and hypoxia-inducible factor (HIF)-1α in a variety of cancers, and siRNA-mediated knockdown of NOX4 inhibited VEGF-induced endothelial cell migration and proliferation." (PMID 29065504, 2017).
cancer (continued). "NOX4, the non-mitochondrial ROS-producing NADPH oxidase, which is highly expressed in BRCA 56 was previously reported to promote cancer cell proliferation, metastasis, transformation and to induce resistance to radiation 56-59." (PMID 34803511, 2021). "The expression of NOX4 and SORT1 were also significantly increased in aggressive cancer tissue when compared with non-malignant (P ≤ 0.01) and indolent cancer tissue (P ≤ 0.05)." (PMID 26473288, 2015). "p22phox is also the functional partner of other NOX isoforms such as NOX1, NOX3 and NOX4, and its lack of expression indicates that ATC cancer cells do not express these NADPH oxidase systems and consequently do not produce superoxide and H2O2 on their own." (PMID 21811634, 2011). "However, NOX1 appears to be a general cancer promoting factor, especially in CRC while NOX4 by itself was not shown to promote CRC progression." (PMID 28423654, 2017). "Specifically, AK2 mediates mitochondrial apoptosis through the formation of an AK2–FADD–caspase 10 complex, whereas NOX4-mediated ROS production induces apoptosis in cancer and normal cells upon stimulation, for instance by incubation with TNF-α, glucose, or anti-cancer drugs." (PMID 31399108, 2019).